APOE (apolipoprotein E)
Diseases named in the same sentence as APOE in open-access papers (continued):
Sharing a sentence is not in itself a finding about the gene and the disease.
cognitive decline (continued). "Previous claims of a gene–environment interaction between APOE ɛ 4 and PA in cognitive decline are not supported by our results." (PMID 32110803, 2020). "In contrast to our findings, a cohort study of 347 older Dutch men found a stronger protective effect of PA in cognitive decline in APOE ɛ 4 carriers compared to noncarriers." (PMID 32110803, 2020). "Our findings are consistent with previous studies that showed a decline of cognitive function with older age in multiple domains, and the negative effect of APOE e4 on cognitive decline in centenarians." (PMID 33488674, 2020). "In general, these discrepancies between the reported rates of cognitive decline in APOE4+ vs. APOE4− AD patients highlight the difficulty of trying to determine a consensus about the contributions of one single trait, such as APOE genotype, on the overall presentation of AD." (PMID 33148345, 2020). "Second, despite the apolipoprotein E (APOE) ε4 being a genetic risk factor for neurodegenerative diseases such as AD and cognitive decline, we did not measure genetic risk factors." (PMID 32370159, 2020). "Why is the relationship between current olfactory impairments and future cognitive decline weaker in ApoE-ε4 non-carriers?" (PMID 31760549, 2020). "They revealed that high expression of NRP1 correlates to a cognitive decline in the patients carrying the APOE-ε4 gene, whereas NRP1 is associated with a beneficial outcome for patients without the APOE-ε4 gene." (PMID 32911833, 2020). "Subjective cognitive decline (SCD) (self-reported cognitive deficits), without measurable cognitive impairment, has been associated with brain structural alterations and APOE-4." (PMID 32357528, 2020). "Compared to non-carriers, APOE ε4 carriers exhibit worse cognitive performance and accelerated cognitive decline in healthy, MCI, and AD subjects." (PMID 30866553, 2019). "Because of the relatively young age of the individual, it is hard to predict if the absence of APOE will lead to exacerbated cognitive decline later on, similar to what is observed in animal models." (PMID 30760557, 2019). "ApoE ε4 carriers had significantly greater cognitive decline compared to non-carriers over the follow-up period." (PMID 30991617, 2019). "However, the exact interplay between the APOE gene, MDD, cognitive decline, and AD remain largely unresolved." (PMID 31191441, 2019). "Crucially, like in models without education as a covariate, APOE E4 status did not moderate the effects of depressive symptoms, neuroticism and AL on baseline cognitive ability and subsequent cognitive decline." (PMID 29451880, 2018). "The AD-PRS without APOE/TOMM40 SNPs was still associated with AD diagnosis, cognitive decline, proteins and histone coacetylation modules, and brain pathologies - except for cerebral amyloid angiopathy (middle lane)." (PMID 30349450, 2018). "At baseline, APOE E4 carriers had significantly lower cognitive ability, but the rate of cognitive decline did not significantly differ between E4 non-carriers and E4 carriers." (PMID 29451880, 2018). "Our results suggest that APOE E4 status does not moderate the relationships of depressive symptoms, neuroticism, and allostatic load with cognitive ability and cognitive decline in healthy older adults." (PMID 29451880, 2018). "Increased CSF ferritin levels were associated with cognitive decline and predicted progression from MCI to AD, regardless of APOE genotype." (PMID 30488277, 2018). "We evaluated whether APOE genotype affected the progression of amyloid-ß, SVD burden, cortical thinning, and cognitive decline in a longitudinal cohort of patients with subcortical vascular mild cognitive impairment (svMCI)." (PMID 28507298, 2017). "In recent years, many studies have found that brain atrophy in AD and mild cognitive impairment (MCI) patients carrying ApoE ε4 is more prevalent than in non-carriers, and their cognitive decline is also more significant." (PMID 28706481, 2017).
cognitive decline (continued). "It remains unclear if and how the interactions between APOE genotypes and cerebral small-vessel diseases (CSVD) lead to cognitive decline in the long term." (PMID 28574812, 2017). "On the other hand, CSF levels of p-tau (APOE4: p = 0.45, r = −0.18; APOE3: p = 0.65, r = −0.10) and Aβ1-42 did not correlate with cognitive decline in both APOE groups (APOE4: p = 0.78, r = 0.07; APOE3: p = 0.35, r = −0.21)." (PMID 29062035, 2017). "The current longitudinal study is aim to dissect the relationship between APOE genotype and CSVD in a two-years cohort of healthy elderly from ADNI database, and to explore whether there are interactions between APOE and CSVD lead to cognitive decline." (PMID 28574812, 2017). "Because of evidence from the meta-analysis and prior findings that suggest that the effect of TOMM40 on nonpathological cognitive decline is not independent of APOE effects, we performed a series of analyses to test this." (PMID 28800603, 2017). "APOE e4 carriers showed over half a standard deviation more general cognitive decline compared to non-carriers, with particularly pronounced decline in their Speed and numerically smaller, but still significant, declines in their verbal memory." (PMID 27932854, 2016). "In contrast, the APOE ε2-isoform is supposed to has a protective effect, e.g. manifesting in lower incidences of MCI and AD, older age of AD onset, and slower cognitive decline." (PMID 27410431, 2016). "In contrast, a study of 212 PD patients found more rapid cognitive decline (Mattis Dementia Rating Scale) over 4 years in APOE-ɛ4 carriers compared to non-carriers, but these were more advanced cases at study entry with a mean disease duration of 7 years." (PMID 27242557, 2016). "In CN older adults who were APOE ε4 non-carriers, high Aβ was unrelated to cognitive decline in learning and working memory." (PMID 26430784, 2015). "Data from Tg mouse models on the role of apoE on cognitive decline are primarily derived from models that express h-apoE, but without h-Aβ pathology." (PMID 25871877, 2015). "Some of the previous SCI studies investigated APOE genotype and showed that the ε4 genotype but not the non-ε4 genotype was related to future cognitive decline and brain atrophy." (PMID 25093415, 2014). "We have also demonstrated that increased semantic memory activation, along with APOE-ε4 non-carrier status, is protective against future cognitive decline." (PMID 24795624, 2014). "This study shows that male gender, older age, a lower level of education, absence of the APOE ε4 allele, more preserved IADL ability and a higher mean dose of ChEI were significant predictors of slower cognitive decline." (PMID 24099236, 2013). "ApoE ε4 positive patients continued to show cognitive decline, while apoE ε4 negative patients showed slight improvement." (PMID 19305740, 2007). "However, there has been no clinical trial conducted exclusively on APOE-ɛ4 carriers with SCD to prevent cognitive decline." (PMID 40664536, 2025). "Given that targets such as APOE, MMP9, and CLDN5 are linked to not just vascular pathology but also early-stage cognitive decline and neurovascular disturbance, the discovered ligands could be used to develop early intervention techniques." (PMID 41032496, 2025). "Indeed, the expected negative influence of APOE ε44 on cognition increased with age (age × ε44: β = −0.049, SE = 0.003, t = −19.07, P < 0.001), underscoring an age-dependent and accelerated cognitive decline in APOE ε44 carriers." (PMID 39903109, 2025). "The significant main effects observed in both TS and EMS suggest that APOE4 may contribute to broad cognitive decline regardless of HDL-C levels, and further highlight the relevance of stratifying by APOE genotype in cognitive aging research." (PMID 40732946, 2025).
cognitive decline (continued). "Last, it is important to acknowledge that our study population was predominantly White, potentially limiting the generalizability to non-White populations, in whom effects of APOE ε4 on cognitive decline may be less prominent." (PMID 40344552, 2025). "In contrast, APOE genotype effects on MD and ISOVF of the posterior thalamic radiation could reflect localised expansion of ventricles, a well-known feature of AD pathology that correlates with cognitive decline." (PMID 38472178, 2024). "To this end, we compared the rate of cognitive decline in AD patients enrolled in two prospective AD cohorts, the National Alzheimer’s Coordinating Center (NACC) and the Alzheimer’s Disease Neuroimaging Initiative (ADNI), who were stratified by KL-VShet+ and APOE ε4 carrier status." (PMID 37107675, 2023). "Despite the negative studies in trials of patients with active cognitive decline, though, reviews suggest that supplementation in APOE ɛ4 carriers might be promising for prevention." (PMID 37509132, 2023). "However, in a longitudinal cohort, the APOE haplotype, but not the CRP haplotype, was associated with life-long cognitive decline, thus disproving any association between CRP and cognitive decline." (PMID 37445986, 2023). "However, levels of CR did not attenuate APOE-ε4-related declines in executive function or AD-PRS-related cognitive decline." (PMID 36978190, 2023). "APOE-ε4 status increased the odds for cognitive decline and dual decline but not physical decline." (PMID 36891556, 2023). "Therefore, we investigated whether the AD-RAI can predict cognitive decline and progression to AD in patients with MCI carrying APOE ε4." (PMID 35572149, 2022). "Whether an additive or multiplicative potentiation effect of RBD and APOE ɛ4 on cognitive decline in PD exists has not been adequately addressed so far." (PMID 36245388, 2022). "Our goal is to determine whether APOE-ε4 modulates the association between Aβ pathology and WMH, and their prediction of neurodegeneration and cognitive decline in non-demented elderly adults." (PMID 35351867, 2022). "Moreover, the role of apolipoprotein E (APOE) genotypes in cognitive decline in patients with COVID-19 has not been evaluated yet." (PMID 36046159, 2022). "We assume that Aβ pathologies and vascular diseases may play different roles in neurodegeneration and cognitive decline in APOE-ε4 carriers and non-carriers." (PMID 35351867, 2022). "Thus, it remains unclear to what extent the independent aspects of amyloid-β, APOE genotype and AD-PRS are related to cognitive decline in cognitively unimpaired individuals." (PMID 36522743, 2022). "APOE ε4 carriers showed slower cognitive decline in EOAD but not in LOAD in terms of language (P = .005), memory (P = .011), and general cognitive function (MMSE, P = .026), in which language and memory remained to be significant (P < .05) after Bonferroni correction for four multiple tests." (PMID 34127075, 2021). "Additionally, we focus on the role of polymorphisms within the genes for catechol-O-methyltransferase (COMT), apolipoprotein E (APOE), vascular endothelial growth factor (VEGF), and for renin-angiotensin-aldosterone system components, and their contribution to cognitive decline in PD." (PMID 33802165, 2021). "APOE‐ε4+ could promote cognitive decline even with the absence of the LRP1‐T allele, whereas, APOE‐ε4− synergy with LRP1‐T− might act a protective role for a higher cognitive function." (PMID 34387022, 2021). "Some studies show accelerated cognitive decline in APOE ε4 homozygotes but not heterozygotes." (PMID 33397450, 2021). "It is unclear whether these acute TBI processes are influenced by the genetic set up, but in the absence of trauma the E4 variant of apolipoprotein E (APOE4) is associated with reduced BBB function and predicts risks of cognitive decline." (PMID 33712077, 2021). "APOE genotypes affected cognitive decline, whereas PRS did not." (PMID 34041846, 2021).
cognitive decline (continued). "However, pathophysiological studies have shown that APOE ε4 can directly lead to cognitive decline without HDL involvement by affecting Aβ clearance, tau hyperphosphorylation, synaptic plasticity, cell signaling, and neuroinflammation." (PMID 32231559, 2020). "Our findings of the APOE e4 non-carriers on more rapid cognitive decline in AD might be explained by APOE e4 carriers having less brain reserve." (PMID 32770103, 2020). "Moreover, AD patients who are APOE*ε2 carriers exhibit slower cognitive decline compared with non-carriers." (PMID 33148290, 2020). "Compared to the typical AD subtype, the hippocampal-sparing AD subtypes, which are characterized by greater pathology (or atrophy) in the diffuse neocortex, exhibit a younger age at onset, greater non-memory function impairment, lower ApoE ε4 genotype frequency, and faster cognitive decline." (PMID 32967721, 2020). "The APOE ε4 allele can also have an additive effect on LOAD-associated brain glucose hypometabolism, as this allele contributes to glucose hypometabolism even in the absence of neurodegeneration and cognitive decline." (PMID 32859588, 2020). "Furthermore, the association between non-exercise physical activity, particularly when carried out in late-life, and less cognitive decline appears to be more pronounced among APOE ε4 non-carriers." (PMID 31798373, 2019). "For other important covariates, high diet quality was associated with a lower risk of global cognitive decline (MoCA-T) in elders aged 65–74 (AOR = 0.42, 95% CI = 0.20–0.88, ptrend = 0.02) and APOE e4 non-carriers (AOR = 0.49, 95% CI = 0.27–0.91, ptrend = 0.02)." (PMID 31330854, 2019). "When global cognitive decline was defined as a loss of ≥3 SMMSE points over 5 y (representing clinically meaningful change), the risk was 3-fold higher in participants belonging to DP3 and was not reduced by apoE ε4 status." (PMID 26740685, 2016). "Additionally, physical activity can affect the apolipoprotein E (APOE) genotypes which were divided as APOEε4 carriers (ε2/ε4, ε3/ε4, and ε4/ε4 genotypes) and noncarriers (ε2/ε2, ε2/ε3, and ε3/ε3 genotypes) because APOE can affect cognitive decline." (PMID 27819000, 2016). "Compared to the APOE E4 noncarriers, the APOE E4 carriers showed a steeper cognitive decline." (PMID 25530658, 2014). "However, the researchers neither considered the APOE genotype nor cognitive decline." (PMID 40167963, 2025). "Third, we noticed that APOE-ε4 carriers with hypertension showed faster rates of cognitive decline than those without hypertension, but the interpretation of this findings may be limited due to the relatively small sample size (n = 18) of APOE-ε4 carriers with hypertension." (PMID 35351867, 2022). "Furthermore, our interaction effects may help to explain the faster disease progression as well as the stronger relationship between Aβ and cognitive decline in APOE-ε4 carriers compared to non-carriers." (PMID 35236958, 2022). "Although it may seem more logical for CSF apoE rather than plasma apoE to be correlated with brain pathology and CSF markers thereof, APOE ε4 status and cognitive decline, previous studies have indeed shown that CSF apoE levels are not affected by these parameters." (PMID 36002891, 2022). "We have shown that both APOE-ε4 and GBA mutations have an independent and additive effect on cognitive outcomes, adding to mounting evidence that these variants are key drivers of cognitive decline in PD, whilst common variants in SNCA and MAPT showed no significant impact." (PMID 35106798, 2022). "However, the interaction between CR indicator and APOE ε4 on cognitive decline was not significant." (PMID 34493618, 2021). "Supporting this notion, some have found that the presence of one or more APOE ε4 alleles is linked to poorer cognition, specifically among older adults, and cognitive decline (as opposed to baseline cognition) may be more sensitive to differences in the APOE ε4 status." (PMID 33716715, 2021).
cognitive decline (continued). "Age (t = −2.28; P = .02), but not sex (t = 0.92; P = .36) or APOE genotype (t = 1.06; P = .29) modified the association between baseline [18F]flortaucipir PET and cognitive change, such that older individuals showed faster cognitive decline at similar tau PET levels." (PMID 34180956, 2021). "In aMCI subjects, females but not APOE e4 allele carriers had significantly lower MOCA scores at baseline but there was a marginally significant (p = 0.054) relationship between carriers of the APOE e4 allele and higher rates of cognitive decline as measured by change in the MOCA." (PMID 32108148, 2020). "Therefore, this study investigated the correlation between urinary AD7c-NTP and ApoE genotype and explored whether urinary AD7c-NTP is affected by other factors that may lead to cognitive decline, further demonstrating the feasibility of urinary AD7c-NTP as a biomarker of AD." (PMID 32587611, 2020). "In contrast to the APOE-ε4 results, AD-PRS-related cognitive decline was not attenuated by level of CR." (PMID 36978190, 2023). "A recent study showed that APOE ε4 carriers exhibit BBB dysfunction and cognitive decline independent of AD pathology." (PMID 35139885, 2022). "Although the P-value of the three-way interaction was not significant, a plot of the interaction between APOE ε4 and ILA on cognitive decline showed that this interaction was principally driven by female participants." (PMID 34616288, 2021). "Previous studies have detected cumulative effects of APOE ε4 carriage and BDNF Val66Met carriage on cognitive decline; however, our study was not sufficiently powered to examine the APOE*BDNF interaction." (PMID 33522961, 2021). "ApoE ε4 carriers exhibit faster cognitive decline 3, 4, increased amyloid β deposition 5, higher NFT density 6 and increased glucose hypometabolism 7 than ApoE ε4 non-carriers." (PMID 31410194, 2019). "Using logistic regression adjusting for age, apolipoprotein E (APOE) ε4 carrier status, sex, years of education, and CCI, the MCP-1 level for the cognitive decliner group was higher than that for the cognitive non-decliner group (p = 0.02)." (PMID 29352259, 2018). "Brain Aβ in relation to the rate of cognitive decline during the decade prior to PET scan among non-demented participants, stratified by APOE ε4 genotype, ethnicity, and gender." (PMID 26221954, 2015). "In contrast, in the complete absence of apoE, the mutant APP gene and its product Aβ are harmless, generating neither amyloid deposits, synaptic disfunction, or cognitive decline, with one copy of apoE having an intermediate effect." (PMID 22844635, 2012). "The findings of the present study provide evidence that polymorphism in TOMM40 ‘523’ may also have significant effects on cognitive decline and progression to PDD, independent of the influence of APOE ε4." (PMID 34234128, 2021). "Finally, subjects with available APOE genotype data were small, so we did not consider the influence of APOE4 on cognitive decline." (PMID 34717581, 2021). "Moreover, the earlier onset of cognitive decline in TBI+ vs. TBI– subjects was independent of sex, race, attained education, APOE genotype, and importantly, clinical diagnoses." (PMID 34054681, 2021). "Furthermore, APOE e4 carrier showed more rapid cognitive decline than APOE e4 non-carrier from SMI to L-aMCI while in AD, APOE e4 non-carrier showed more rapid cognitive decline than APOE e4 carrier." (PMID 32770103, 2020). "Additionally, increased levels of CSF MMP-9 were found in individuals exhibiting low Aβ levels, high tau levels, and APOE ε4 positivity, compared to those with negative biomarkers, indicating a significance of MMP-9 in the early pathophysiology of AD, even preceding cognitive decline." (PMID 38891891, 2024).